CCL26 (C-C motif chemokine ligand 26)
Diseases named in the same sentence as CCL26 in open-access papers (continued):
Sharing a sentence is not in itself a finding about the gene and the disease.
ulcerative colitis (2 papers, 2021 to 2023). An inflammatory bowel disease involving the mucosal surface of the large intestine and rectum. "MiRNA-31-5p is also elevated in inflamed ulcerative colitis mucosa, where it suppresses the expression of signal transducer and activator of transcription 6 (STAT6), suppressor of cytokine signaling 1 (SOCS1), and eotaxin-3 (CCL26) via downregulating the IL-13 receptor α-1 (IL13Rα-1) gene." (PMID 37559103, 2023).
atrophic gastritis (1 paper, 2020). "In an atrophic gastritis environment, the expression of CXCL14, CCL4, CCL26, CCL21, CCL2, CCL19, and CCL13 was correlated with the infiltration of central memory CD4 T cell." (PMID 33426088, 2020). "In superficial gastritis and atrophic gastritis, the expression levels of chemokines/interleukins are relatively the same (IL14, CXCL14, and CCL28 had higher expression levels; IL3, CCL26, IL31, etc., had lower expression levels), only with a slight difference." (PMID 33426088, 2020).
colorectal polyp (1 paper, 2022). "In this work, we studied the colorectal polyp-confined tissue containing eosinophils and we hypothesized that intestinal epithelial cells are the cell source of eotaxin-3 or CCL26, a potent chemoattractant for eosinophils." (PMID 35799778, 2022).
eczema (1 paper, 2022). "Accordingly, we demonstrated that HVE and HT may counteract the release of CCL26 using keratinocytes, thus sustaining the possible role of HVE in controlling pruritus and eosinophilic infiltration in eczema." (PMID 36012541, 2022).
endometrial cancer (1 paper, 2025). Primary or metastatic malignant neoplasm involving the endometrium (mucous membrane that lines the endometrial cavity). "For instance, CCL26 overexpression correlates with poor prognosis in lung, liver, renal, and urothelial cancers, while in stomach, pancreatic, and endometrial cancers, higher levels are associated with longer overall survival." (PMID 39931245, 2025).
glioblastoma (1 paper, 2010). The most malignant astrocytic tumor (WHO grade IV). "We demonstrated that these glioblastoma cells were put into relatively cytokine "rich" environment produced by AT-MSC containing IL-1β, IL-1ra, IL-2, IL-4, IL-6, IL-8, TNF-α, IFN-γ, CCL5, CCL26, CXCL10, PDGF-bb." (PMID 20509882, 2010).
head and neck cancer (1 paper, 2025). A primary or metastatic malignant neoplasm affecting the head and neck. "Single-cell sequencing from the TISCH2 database showed CCL26’s broad distribution across various cell types, including tumor cells, mesenchymal stromal cells, and immune cells in head and neck cancers (GSE103322)." (PMID 39931245, 2025). "Notably, in head and neck cancers, CCL26 expression was 4–5 times higher in tumor tissues than in normal counterparts." (PMID 39931245, 2025).
Hodgkins lymphoma (1 paper, 2025). A heterogeneous group of malignant lymphoid neoplasms of B-cell origin characterized histologically by the presence of Hodgkin and Reed-Sternberg (HRS) cells in the vast majority of cases. "In Hodgkin lymphoma and cutaneous T cell lymphoma (CTCL), CCL26 recruits CCR3+ T lymphocytes into TIME, where they secrete high levels of IL-4—a hallmark of a T helper 2 (Th2)-dominant microenvironment that is closely associated with CTCL development." (PMID 41280721, 2025).
Hypoxemia (1 paper, 2023). An abnormally low level of blood oxygen. "Hypoxemia is a key regulatory factor that induces MDSCs accumulation via the chemokine C-C motif Ligand 26 (CCL26)/CX3CR1 pathway." (PMID 36845131, 2023).
liver cancer (1 paper, 2023). An epithelial or non-epithelial malignant neoplasm that arises from the liver. "The high expression of FARSB may constitute an immunosuppressive microenvironment by affecting the expression levels of relevant chemokines, CCL26 and CX3CL1, and helping the infiltration of Th2 cells, resulting in a poor prognosis for liver cancer patients." (PMID 37074800, 2023). "Therefore, the high expression of FARSB may constitute an immunosuppressive microenvironment by affecting the expression levels of relevant chemokines, CCL26 and CX3CL1, and helping the infiltration of Th2 cells, resulting in a poor prognosis for liver cancer patients." (PMID 37074800, 2023).
mastitis (1 paper, 2020). Inflammation of breast tissue during lactation or postpartum due to an obstructed duct or infection. "Five genes (EPOR, IL9, IFNL3, CCL26, and IL26) that were involved in this pathway might serve as potential molecular markers for breeding programs that enhance resistance to S. aureus infection and mastitis." (PMID 32944235, 2020).
mild cognitive impairment (1 paper, 2012). "We therefore measured the levels of CCL2 and three other CCR2 ligands, i.e. CCL11 (eotaxin), CCL13 (MCP-4) and CCL26 (eotaxin-3), in the cerebrospinal fluid (CSF) and plasma of 30 controls and 119 patients with mild cognitive impairment (MCI) at baseline." (PMID 22303443, 2012).
neuromyelitis optica spectrum disorder (1 paper, 2018). "Adjusted regression coefficients (β) of CCL13, CCL11, and CCL26 levels with relapse times, ARR, and EDSS scores as outcomes in neuromyelitis optica spectrum disorder patients." (PMID 29497397, 2018).
neuronal tumor (1 paper, 2020). Neuronal brain tumors are an uncommon group of central nervous system tumors that arise from cells with neuronal differentiation. "Interestingly, the effect of VX765 treatment differed in neuronal tumors where elevated levels of CCL11 and CCL26 were found in SH-SY5Y compared to untreated controls, and no changes in cytokine levels were detected in VX765 treated U138MG cells compared to controls." (PMID 33613529, 2020).
neuropathy (1 paper, 2021). A disorder affecting the nervous system that manifests with pain, tingling, numbness, and/or muscle weakness. "Interestingly, according to Bonferroni’s post hoc test, mRNA levels of those two chemokines together with CCL26 were upregulated on day 28 after injury, which may prove their important roles in the maintenance of neuropathy." (PMID 34795678, 2021).
ovarian carcinoma (1 paper, 2020). A malignant neoplasm originating from the surface ovarian epithelium. "Chronic hypoxia increases CCL26/eotaxin-3 expression in ovarian cancer cells." (PMID 32781743, 2020).
pancreatic adenocarcinoma (1 paper, 2022). "They further suggested that CCL26 enhanced the invasive ability of pancreatic adenocarcinoma cells through activation of PI3K/AKT/mTOR axis." (PMID 35770088, 2022).
pemphigus (1 paper, 2022). Pemphigus is a group of rare autoimmune diseases that cause blistering of the skin and mucous membranes (mouth, nose, throat, eyes, and genitals).This conditioncan occur at any age, but often strikes people in middle or older age. "Notably, CCL19, CCL26, CCL27 and CXCR5 were highly expressed chemokines and chemokine receptors detected in pemphigus group." (PMID 35449056, 2022).
renal fibrosis (1 paper, 2022). A final common manifestation of a wide variety of chronic kidney diseases characterized by glomerulosclerosis and tubulointerstitial fibrosis. "In addition, the elevated secretion of pro-inflammatory cytokines, including M1-related CXCL1 and CXCL10 and M2-related CCL17 and CCL26, may augment in the early phase of renal inflammation and in the late phase of renal fibrosis in folic acid-induced RIF." (PMID 35990680, 2022).
tumor (50 papers, 2011 to 2025). "CCL26 exhibited aberrant expression profiles in most solid cancers, which cause tumor microenvironment variation to influence tumor progression." (PMID 39931245, 2025). "It is consistent with most previous studies, CCL26 was highly expressed in tumor cells and cafs and enrichment of these cells is associated with a trend toward decreased overall survival rate, showed a worse prognosis." (PMID 39931245, 2025). "Drugs that directly kill tumor cells also cause significant damage to normal cells, but the focus of this studies an inflammation-specific chemokine, CCL26, usually triggered by eosinophils." (PMID 34518591, 2021). "As expected, we confirmed that the enhancement of CCL26 resulted in the activation of signaling involved in the invasion of tumor cells and phosphorylation of proteins associated with the proliferative capacity, such as ERK." (PMID 34518591, 2021). "Preliminary findings suggest that it may be associated with altered invasive phenotype and tumor immunosuppressive microenvironment, and importantly, the relationship between CCL26 and immune homeostasis and immune checkpoint pathway was also examined." (PMID 39931245, 2025). "Moreover, the expressions of CXCL14, CCL20, CCL24, and CCL26 were associated with tumor purity and infiltration of CD4+ T cell, CD8+ T cell, B cell, macrophage, dendritic cell, and neutrophil in PCa." (PMID 36275733, 2022). "In situ immunohistochemistry of OSCC samples revealed widespread CCL26 expression in both tumor cells and CAFs, localized to the cell membrane and cytoplasm." (PMID 39931245, 2025). "CX3CR1 sufficiency enhanced tumor cell CCL26 induction; this effect was attenuated by TGF-β1 blockade and reduced in Cx3cr1cKO PMN-MDSCs." (PMID 41280721, 2025). "We also determined the invasive phenotype of tumor cells with distinct CCL26 level and explored its immune checkpoint and immunocytes relevance by differentially expressed gene (DEG) analysis, GSEA, and GO analysis." (PMID 39931245, 2025). "The clinical spatial distribution pattern of CCL26 in tumor microenvironment was determined, and its clinical outcomes were investigated." (PMID 39931245, 2025). "CCL26 belongs to the CC chemokine subfamily, which consists of 27 chemokines that are essential for cell communication and tumor microenvironment regulation." (PMID 39931245, 2025). "Our prior research showed that CCL26 secreted by CAF in the worst pattern of invasion (WPOI) type 4–5 alters the tumor phenotype and correlates with reduced patient survival." (PMID 39931245, 2025). "RBP4+ and CCL26+ tumor cells demonstrated enrichment in nearly all pathways, indicating their prominence in multiple biological processes." (PMID 38913193, 2024). "The CCL26 binds tightly to HIFs and recruits MDSCs to hypoxic regions of the tumor, indicating that hypoxic mechanisms are closely related to tumor infiltration of MDSCs in HCC-bearing mice models." (PMID 37217620, 2023). "OXTRHigh CAFs are rich in the WPOI 4–5 type stroma and promote ECM remodeling through ERK5 signaling, which, in turn maintains OXTR and CCL26 expression, correlating with an invasive tumor phenotype." (PMID 36045118, 2022). "As before, CCL26 promoted matrix invasion by tumor cells in the OXTRLow CAF/Tumor co-culture model but this was abrogated by CCR3 knockout." (PMID 36045118, 2022). "In this system, only CCL26 knockdown in OXTRHigh CAFs significantly attenuated the invasion length of tumor cells." (PMID 36045118, 2022). "The expression levels of PHTF2, MFAP2, INHBA, TSPAN9, and CCL26 (p < 0.05) displayed tumor stage-dependent alterations." (PMID 34456964, 2021). "Given that CCL26 plays an essential role in inflammatory cell infiltration, it is suspected that it promotes tumor cell infiltration and distant metastasis." (PMID 34518591, 2021). "Research has shown that the expression of CCL26 increases when normal and malignant tumor cells share the same environment." (PMID 34518591, 2021).
tumor (continued). "A more important effect of chemokine CCL26 on the microenvironment of tumor cells is the enhancement of the motility and invasive ability." (PMID 34518591, 2021). "Immunohistochemistry analysis using resected lung tumors demonstrated that the expression of Rac and p-Src was reduced in the anti-CCL26 Ab-administered tumor tissues." (PMID 34518591, 2021). "Hypoxia can promote the secretion of CCL26 by tumor cells to recruit MDSCs, which is the main driver of MDSCs accumulation in tumor immune microenvironment." (PMID 34977159, 2021). "MG63 cells had a higher expression level of CCL26 than hMSCs under single culture conditions; however, the expression of CCL26 was even enhanced when the tumor cells were co-cultured with the normal cells." (PMID 34518591, 2021). "As an illustration, MDSCs arrive to the tumor niche following the trail of tumor-derived CCL26 (C–C motif chemokine ligand 26) in hepatocellular carcinoma." (PMID 32466293, 2020). "Chemokines in the omental tumor tissues revealed some changes as follows: 1) the decreased levels in CCL26, CCL28, CXCL1-3, CXCL8 and CXCL16; 2) the increased level in CCL24; and 3) the conserved level in CCL20 compared to the parental cells." (PMID 27723802, 2016). "Therefore, to better understand how CCL26 influences the OSCC tumor immune microenvironment, we turn to investigate immune checkpoint and immune cell infiltration molecules." (PMID 39931245, 2025). "After we performed enrichment pathway analysis of differential genes, we also found that cell junctional assembly pathways were significantly enriched in the CCL26high group; these findings suggest that CCL26 has the potential to affect tumor cells by regulating EMT." (PMID 39931245, 2025). "Therefore, in this work, we systematically investigated the clinical expression patterns, clinicopathological features, and prognostic value of CCL26 chemokines in the tumor microenvironment (TME)." (PMID 39931245, 2025). "Several immune-related pathways were enriched in the CCL26low group (immunoglobulin mediated immune response, B cell mediated immunity), suggests that CCL26 may play a role in suppressing tumor immunity." (PMID 39931245, 2025). "It is also reasonable to speculate that CCL26 acts an indispensable function in the response to tumor immunotherapy." (PMID 39931245, 2025). "Furthermore, the expression of CCL26 was significantly reduced in mice tumor tissue in which CCL26 was neutralized, and thus the results observed ex vivo were confirmed in vivo." (PMID 34518591, 2021). "Similarly, CXCL5, CXCL13, CCL1, CCL7 and CCL26 in WF collected from patients with T1–2 tumor tend to be higher than those with Tis, and the profiles of CXCL13, CCL27, MMP-1 and MMP-7 in WF from N1–3 patients tend to be higher than those with N0." (PMID 26313265, 2015). "The analysis showed that high expression of CCL26 downregulated KRT36, which is a keratin family member previously thought to be inactivated during tongue tumorigenesis, resulting in the loss of epithelial features of tumor cells, and closely associated with the onset of the EMT process." (PMID 39931245, 2025). "Finally, tumor-derived CCL26 could induce MDSC chemotaxis and recruitment to tumors, and both, blocking of CCL26 receptor and treatment of HIF inhibitor Digoxin, suppressed tumor growth." (PMID 38786066, 2024). "Thus, CCL26 in OXTRHigh CAFs had a relatively superior ability to promote tumor invasion." (PMID 36045118, 2022). "Several CAF-derived chemokines such as CCL2, CCL26, IL6, CXCL1, and CXCL8 mediate tumor progression, angiogenesis, and drug resistance, suggesting that tumor–CAF crosstalk is a bidirectional, dynamic, and adaptive process." (PMID 40447617, 2025). "CCL26 was upregulated in HNSC and preferentially high-expressed on CAFs and tumor cells in OSCC patients, which exhibits a trend toward decreased overall survival." (PMID 39931245, 2025).
tumor (continued). "Another report showed that interaction of CCL26 and CCR3 regulates the Th2-dominant tumor environment." (PMID 39931245, 2025). "The qRT-PCR results demonstrated that four cellular senescence-related genes (CENPA, CXCL8, EZH2, and G6PD) and two chemokine-related genes (CCL26 and CXCL5) were overexpressed in tumor tissues from HCC patients compared with paraneoplastic tissues." (PMID 36670201, 2023). "With further growth of the tumor, the immune response gradually changed from anti-tumor to pro-tumor mode, and the high concentration of CCL26 and CCL11 in the TME recruits Th2 cells to the tumor area." (PMID 37063892, 2023). "During tumor progression, Th2 cells are recruited to the TME by CCR3 ligands (CCL26, CCL11, and so on), and produce IL-4 and IL-10, which induce M2 polarization of macrophages." (PMID 37063892, 2023). "Similar to our previous results, CCL18, CCL26, and LIGHT had the most dramatic effects in promoting OXTRLow CAFs-induced HN6 invasion, but only knockdown of CCL26, and with a lesser extent of CCL18, impaired OXTRHigh CAFs-dependent tumor invasion." (PMID 36045118, 2022). "As expected, the expression of CCL14, CCL25, CCL26, and CCL28 were obviously related to the pathological stage, and with the aggravation of tumor malignancy, the expression of CCL25, CCL26, and CCL28 were increased while CCL14 was decreased." (PMID 34938730, 2021). "Patients with low PD-L1 levels displayed a strong trend towards an impaired prognosis, and circulating PD-L1 was negatively correlated with experimental markers of promalignant tumor characteristics such as CCL1, CCL21, CCL25 and CCL26." (PMID 34207359, 2021). "CCL26 and CCR8 are related to the Ca2+ mobilization of cells, and CCR8 can also recruit Treg infiltration, thereby promoting tumor metastasis." (PMID 33330624, 2020). "Migration to the TME can be mediated by eotaxins (eotaxin-1/CCL11, eotaxin-2/CCL24, eotaxin-3/CCL26) that bind the CCR3 receptor highly expressed on eosinophils and by alarmins (i.e., HMGB1 and IL-33) released from dying tumor cells." (PMID 33329534, 2020). "Blockade of CCL26 cognate receptor, CX3CR1, by neutralizing antibody prevented MDSC infiltration and perturbed tumor growth." (PMID 28894087, 2017). "It has been demonstrated that tumor cells release inflammatory cytokines (IL-6, IL-1, TNF-α), chemokines (CCL2, CCL5, CCL15, CCL26), and growth factors (TGFβ), which ultimately recruit BMDCs such as myeloid-derived suppressor cells (MDSCs) and create a favorable niche for tumor development." (PMID 41383620, 2025). "Notably, expression levels were higher in tumor cells, consistent with our previous findings on CAF-derived CCL26’s role in tumor invasiveness." (PMID 39931245, 2025). "Our prior research showed that CCL26, secreted by CAFWPOI4-5, promotes altered tumor invasiveness." (PMID 39931245, 2025). "Exceptions to this pattern were IL1B, which was transcribed predominantly by myeloid cells irrespective of the CALB1 status of the tumor, and CCL26, which was transcribed predominantly by CALB1-expressing cancer cells." (PMID 37192000, 2023). "Similarly, CCL26 also showed a moderate correlation with higher SLC3A2 expression across cancer types, which has been reported to be a key element in tumor invasion and chemoresistance." (PMID 35992269, 2022). "The humoral factor CCL26 does not come into direct contact with the tumor cells, but it is intimately involved in the development of distant lesions." (PMID 34518591, 2021). "Moreover, significant differences were found in the expressions of INHBA, CCL26, MFAP2, TSPAN9, and PHTF2 in tumor stage based on TCGA-ESCA, suggesting their prognostic value in ESCC tumor development." (PMID 34456964, 2021). "Furthermore, inhibition of CCL-26 by the HIF inhibitor digoxin or through the blockade of CX3CR1 using a neutralizing antibody suppressed MDSC recruitment and tumour growth." (PMID 31835751, 2019).
tumor (continued). "Among tumor-related factors involved in the generation of MDSCs and their recruitment from bone marrow to tumor microenvironment are mediated by granulocyte–macrophage colony-stimulating factor (GM-CSF), IL-6, indoleamine 2,3-dioxygenase (IDO) and chemokines (e.g. CCL26, CXCL12, CXCL8)." (PMID 35589776, 2022). "However, other CCLs, including CCL2, CCL3, CCL11, CCL26, and CCL28, did not exhibit significant changes in expression during tumor progression." (PMID 39859340, 2025).